CCL20 (C-C motif chemokine ligand 20)
Diseases named in the same sentence as CCL20 in open-access papers (continued):
Sharing a sentence is not in itself a finding about the gene and the disease.
tumor (continued). "In addition, the expression levels of CCL20 have also been reported to be frequently elevated in tumor tissues of various types of cancer and to correlate with Th17 cell infiltration." (PMID 34885241, 2021). "In addition, C/EBPδ supported the expression of the chemokines CXCL8 (IL-8) and CCL20, which are known for their tumor promoting and immunosuppressive properties." (PMID 34725321, 2021). "Indeed, IL-37 overexpression in HCC cells is related with the recruitment of more DCs into the tumor tissues by secreting high levels of specific chemokine, such as CCL3 and CCL20, significantly reducing tumor growth." (PMID 34248996, 2021). "Moreover, the depletion of TAM in a murine CRC model strongly decreased CCL20 production, leading to tumor growth inhibition." (PMID 33924428, 2021). "Hence, as research advances, it would be better to understand the communication networks between CCL20 and other factors in the tumor microenvironment." (PMID 34569432, 2021). "Furthermore, immunohistochemical analysis revealed a positive correlation between CCL20 and CD66b+ neutrophils in tumor tissues, which further supports a possible interaction between CCL20 and TANs in tumor microenvironment." (PMID 34519637, 2021). "Moreover, in human tumors (esophageal SCC, NSCLC and HNSCC), CCL20 favors the recruitment of Th17 CD4+ T cells that also participate in tumor progression." (PMID 33924428, 2021). "Furthermore, the results of tissue samples have demonstrated that both CCL5 and CCL20 were markedly upregulated in HCC tumor tissues than in adjacent tissues." (PMID 34938730, 2021). "Moreover, CCL20 enhances the protumoral effects on both tumor cells and stromal cells via ERK phosphorylation in various cancers." (PMID 34178651, 2021). "Tumor-derived CCL20 activated and upregulated PD-L1 expression on neutrophils." (PMID 34519637, 2021). "Evidence has shown that Tregs are induced to invade tumor tissues by CCL20." (PMID 34569432, 2021). "Evidence has shown that Treg is induced by CCL20 and invades tumor tissue, but CCL20 may be derived from tumor cells, macrophages, and other stromal cells." (PMID 32707869, 2020). "Thus, the observed increase in the circulating levels of CCL20 indicates a probable migration of T cells to the tumor microenvironment of these carcinomas." (PMID 32256215, 2020). "Thus, a Ccr6-positive immune system did not significantly affect tumour growth, indicating that the action of CCL20 on angiogenesis is more important during tumour progression than its role in immune cell recruitment in this model." (PMID 32601464, 2020). "Expression of CCL20 was mainly found in cytoplasm of tumor cells." (PMID 32573058, 2020). "iDCs are attracted to tumor tissue sites through CCL20, CXCL12, and CXCL14 chemotaxis." (PMID 31991604, 2020). "In contrast, Th17-derived IL-17 is also shown to promote anti-tumor immunity by enhancing IFN-γ+ NK- and effector T cell activation and CCL20-dependent tumor and draining lymph node infiltration of DCs resulting in increased antigen-specific activation of CTLs." (PMID 33324425, 2020). "Tumours facilitate progression by the EGFR/Ras-induced production of CCL20." (PMID 32601464, 2020). "CCL20 is a chemokine ligand which is known to promote tumor cell proliferation and migration." (PMID 32508847, 2020). "We also examined CCL20 expression in relation to tumour grade." (PMID 32601464, 2020). "EVs derived from DCs exposed to hyperthermia and stress contain increased amounts of heat shock proteins and chemokines (CCL2, CCL5, and CCL20) and as such, promote infiltration of tumor-attacking T cells and DCs into the tumor microenvironment of mice treated with these EVs." (PMID 32765528, 2020). "Further, we showed that knockdown of CCL20 suppressed cell proliferation, apoptosis escape, clonogenesis, migration and invasion in PC cell lines, suggesting CCL20 might be crucial to regulate tumor progression in PC." (PMID 33123272, 2020).
tumor (continued). "CXCL12 and CCL20 were shown to be stimulatory chemokines related to tumor neovascularization." (PMID 32775427, 2020). "CCL20 is a tumor-promoting chemokine, and induces EMT and cell migration." (PMID 33003572, 2020). "Furthermore, CCL19/CCR7, CXCL12/CXCR4, and CCL20/CCR6 were shown to be potential new targets for tumor gene therapy in type 2 PRCC." (PMID 32775427, 2020). "However, as suggested by Lu, tumor-infiltrating Th9 cells induced lung epithelial cells to express CCL20 and then recruited DCs to tumor sites." (PMID 32508847, 2020). "Interestingly, chemotherapy with CP stimulates CAMs to secrete CCL20, then the CCL20/CCR6 axis enhances tumor cell migration and induces the EMT mechanism, thereby leading to EMT-mediated drug resistance." (PMID 32503307, 2020). "Treg is recruited by not only tumor cells but also TAM-derived CCL20, which may lead to cancer progression and poor prognosis among patients with HCC, CRC, and RCC." (PMID 32707869, 2020). "The results showed that the expression of CCL20 was upregulated in FOXO1(+) tumor cells." (PMID 33052231, 2020). "The fact that CCR6-positive vessels are closely apposed to CCL20-expressing tumours allowed us to hypothesise that CCL20 might be able to functionally activate the microvasculature and induce angiogenesis." (PMID 32601464, 2020). "Enhanced CCL20 production in EBNA1‐expressed tumor cells increased Tregs migration." (PMID 32573058, 2020). "Enhanced CCL20 production in EBNA1‐expressed tumor cell increased Tregs migration." (PMID 32573058, 2020). "Moreover, CCL20 plays a role in the progression of CRC by inducing TAM into tumor tissues and promoting TNFα secretion in TAM." (PMID 32707869, 2020). "F. nucleatum might also contribute to aggressive tumor behavior through the activation of chemokines, such as chemokine (C-C motif) ligand 20 (CCL20)." (PMID 33193429, 2020). "Thus, we conclude that the main role for expression of CCL20 in the tumour microenvironment is to stimulate recruitment of vessels into the growing tumour mass, resulting in faster growth and progression of the tumour." (PMID 32601464, 2020). "And further research has shown that EBNA1+ HL cells mediate overexpression of CCL20 which could recruit regulatory T cells migrated into tumor." (PMID 32573058, 2020). "The main primary function of CCL20 in a tumor is to recruit Treg and Th17 for the tumor niche." (PMID 33076281, 2020). "Additionally, the IHC results further validated the co-localization of FOXO1 and CCL20 in ESCC tumor tissues." (PMID 33052231, 2020). "Furthermore, CRC cells secrete CCL20 and recruit Treg into tumor tissues, enhancing their chemoresistance." (PMID 32707869, 2020). "To test our hypothesis that tumour-derived CCL20 might participate in tumour angiogenesis, we investigated the effect of CCL20 on microvascular endothelial cells in vitro." (PMID 32601464, 2020). "The presence of extensive tumor-associated macrophage infiltration into the RCC microenvironment contributes to cancer progression and metastasis by stimulating angiogenesis, tumor growth, cellular migration and invasion, as well as recruitment of Tregs to the tumor site by secreting CCL20 or CCL22." (PMID 35582435, 2020). "The observation that Ccl20 was able to promote vessel formation in the Matrigel plugs suggests that, in the tumour microenvironment, CCL20 may be able to induce and/or enhance tumour angiogenesis." (PMID 32601464, 2020). "CCL20 blockade suppressed tumor progression and restored 5-FU sensitivity in CRC." (PMID 31395078, 2019). "In addition, CCL20 mRNA expression was positively correlated with FOXP3 expression in tumor tissues (r = 0.323, P = .04)." (PMID 31852159, 2019). "CCL20 is known to play an important role in tumor progression." (PMID 31395078, 2019). "The effects of CCL20 on Tregs may be to recruit existing FOXP3+ Tregs to tumor sites and inducing the expansion of retained Tregs, thereby synergistically carrying out immunosuppression." (PMID 31852159, 2019).
tumor (continued). "IL-17A has also been shown to enhance CCL20 production in various tumor cells." (PMID 31387598, 2019). "We next investigated whether the expression of FOXO1/CEBPB/NF-κB/CCL20 signaling molecules had prognostic value using tumor tissues from CRC patients." (PMID 31395078, 2019). "Immunohistochemistry results showed that CCL20 expression in tumor tissues was obviously higher than that in peritumor tissues (P < 0.001), and similarly higher levels were observed in tumor tissues from Folfox-resistant patients who received neoadjuvant chemotherapy." (PMID 31395078, 2019). "These actions of CCL20 resulted in the acquisition of a more aggressive behavior by the tumor." (PMID 29977225, 2018). "Then, rescue assays by proliferation assay (real-time cellular analysis, RTCA) and transwell assays revealed that overexpression of u50535, which promotes tumor cell growth and migration, could be reversed after CCL20 downregulation." (PMID 29970882, 2018). "However, CCL20 administration in CCR6+ tumor bearing mice increased tumor weight and numbers of spontaneous lung metastases suggesting the potential involvement of CCR6 in lung metastasis formation." (PMID 30420855, 2018). "In addition, we found that CCL20 was elevated in the tumor residue of MDA-MB-231 xenograft tumor model in the docetaxel treatment group, in contrast to the control group, as analyzed by immunohistochemistry (IHC) staining." (PMID 30052635, 2018). "Furthermore, the same group of researchers introduced a dual anti-cancer mechanism by modulating the CCR6/CCL20 axis in a tumor environment." (PMID 30453514, 2018). "The roles of CCL20 in cancer development, tumor promotion, and metastasis are linked to the attraction of CCR6-expessing regulatory T lymphocytes to tumor sites expressing CCL2046–49 and to the recruitment of CCR6-expressing cancer cells to metastatic sites with abundant CCL2050." (PMID 28851919, 2017). "Furthermore, reduced expression of CCL20 and GM-CSF was observed in tumor tissues from mice intracardially injected with shHuR cells based on immunohistochemical examination." (PMID 28851919, 2017). "In addition, it is well known that CCL3, CCL4 and CCL20 are able to recruit T cells containing CTLs to the tumor site." (PMID 29079795, 2017). "We suppose that CCL20 may promote cancer progression by a direct action on cancer cells or establishing a microenvironment that suppresses specific anti‐tumour response." (PMID 26968871, 2016). "IL-17A could promote the ESCC tumor cells to produce more chemokines CCL2, CCL20 and CXCL13, which were associated with the migration of B cells." (PMID 26942702, 2016). "Our study provides at least a clue that FOXP3+ Tregs migration to tumours may be due to recruitment to CCL20." (PMID 27725696, 2016). "This configuration may be responsible for Th17 lymphocytes stagnation in the tumor microenvironment where the levels of CCL20 and CXCL12 are high." (PMID 27589729, 2016). "Interestingly we were able to quantify the expression in tumor bearing mice of the human chemokines IL-11 and CCL20, known as key players in the regulation of cancer cell migration and progression from different solid tumors." (PMID 27322553, 2016). "Our findings provided clues that FOXP3+ Tregs migration to tumours may be due to recruitment to CCL20." (PMID 27725696, 2016). "Indeed, cytokines and growth factors such as IL-10,TGF-β, and VEGF areoverexpressed in tumor tissue just as the chemoattractant factorsMIP-3α/CCL20 are." (PMID 27795841, 2016). "Furthermore, chemoattractive roles of CCL20 in the tumour cell recruitment and proliferative roles of CCL20 in the tumour growth were investigated, and the involvement of ERK1/2‐MAPK and PI3K pathway in these processes was monitored." (PMID 26968871, 2016). "The findings that CCL20 accelerated the migration and growth of cancer cells indicate that CCL20 may play the role in the maintenance of tumour growth and reconstruction of tumour tissues." (PMID 26968871, 2016).
tumor (continued). "Although the function of CCL20 in RCC stem cell-mediated bone metastasis needs further investigation, it is tempting to speculate that blocking CCL20 signaling could be useful to inhibit both bone metastases and tumor immune escape." (PMID 27322553, 2016). "Moreover, the higher level of CCL20 in both serum and tumor tissue was detected in orthotopic transplantation mouse models." (PMID 27015366, 2016). "CCR6 is being identified as a potential new prognostic marker in some types of tumours and the axis of CCL20/CCR6/IL-17 may be a new therapeutic target in cancer." (PMID 26626416, 2015). "Our previous study investigated whether the expression of CCL20 and CCR6 was correlated with the development of UC-associated neoplasia in adult UC patients." (PMID 25691899, 2015). "Because Ccl2 and Ccl20 are critical inflammatory mediators, their expressions were also determined by real-time PCR and Western blot methods on day 28 to investigate additional mechanisms involved in the anti-tumor immunity of IL-17." (PMID 26684834, 2015). "However, the identification of tumor-metastasis-related genes regulated by the CCR6/CCL20 axis will be clinically important for designing targeted therapies for the treatment of CRC in the future." (PMID 24979261, 2014). "We next sought to determine the cells in the tumor microenvironment that express CCL20." (PMID 24866282, 2014). "Finally, Th17 cells that have homed to the tumor – due to their vast chemokine expression – can stimulate tumor tissue to produce chemoattractants (i.e., CCL20), which then recruit CTLs to the tumor." (PMID 24987392, 2014). "The IHC score for CCL20 expression in the patients with UC-associated neoplasia was higher compared with the patients without neoplasia (P=0.0294)." (PMID 24179507, 2013). "The present study investigated whether an evaluation of CCL20 and CCR6 expression in the rectal mucosa would be useful for predicting the development of UC-associated neoplasia." (PMID 24179507, 2013). "The IHC score for CCL20 in the UC-associated neoplasia group was higher than in the non-neoplasia group (P=0.0294)." (PMID 24179507, 2013). "Moreover, Th17 cells have been shown to produce the chemokine CCL20 which can promote DC trafficking to the sites of tumor growth in a CCL20-CCR6 dependent manner." (PMID 23533029, 2013). "Perhaps the most compelling evidence that tumor-derived chemokines influence the type of DCs found in the tumor has been demonstrated in a renal-cell carcinoma model, where the intra-tumoral or peri-tumoral distribution of DCs is determined by CCL20 and CCL19 levels." (PMID 24339824, 2013). "A positive feedback cycle may be formed in the tissue environment: CCR6+ memory TH17 is homed to tumor site by high levels of CCL20." (PMID 23316374, 2012). "We speculate that IL-17-induced CCL20 production in the tumor microenvironment may act in an autocrine manner to stimulate tumor cell growth and in a paracrine manner to enhance the tumor-associated inflammatory response." (PMID 21949768, 2011). "To determine whether macrophages are responsible for the overproduction of CCL20 in the tumor mass, we co-cultured CMT93 cancer cells with fresh mouse peritoneal macrophages for 48 hrs in a transwell apparatus." (PMID 21559338, 2011). "We infer this may result from the strong expression of CCL20 in tumor environment, which inversely internalizes the CCR6 expression like CCR4." (PMID 21935436, 2011). "CCL20 was highly expressed in the majority (38/49, 77.5%) of tumor samples." (PMID 21949768, 2011). "However, we observed that, in HCC patients, circulating Tregs highly express CCR6 and migrate to CCL20 present in the tumor microenvironment." (PMID 21935436, 2011). "Moreover, the CCL20 expression was strong correlated with the number of FoxP3+ Tregs in tumor environment." (PMID 21935436, 2011). "Furthermore, we evaluated the relationship of Tregs to CCL20 in the same tumor environment by immunohistochemistry." (PMID 21935436, 2011).